TP63 (tumor protein p63)
Diseases named in the same sentence as TP63 in open-access papers (continued):
Sharing a sentence is not in itself a finding about the gene and the disease.
cancer (continued). "Moreover, SREBF1 shows a noncanonical, SCC-specific function by cooperating with TP63/KLF5 to regulate hundreds of cis-regulatory elements across the SCC epigenome, which converge on activating cancer-promoting pathways." (PMID 34272396, 2021). "Here, we observed that TP63 and SOX2 co-bound to the promoter and super-enhancer regions of CCAT1 and contributed to its transcription activity specifically in SCCs, but not other cancer types." (PMID 30190462, 2018).
adenocarcinoma (21 papers, 2011 to 2025). A common cancer characterized by the presence of malignant glandular cells. "To understand these signatures in more detail, we explored the expression of canonical markers of adenocarcinoma and squamous differentiation, namely NAPSA (which encodes Napsin A) and TP63 (which encodes both p63 and p40), respectively." (PMID 37024582, 2023). "Thyroid transcription factor 1 (TTF-1) was used as a specific marker for adenocarcinomas, while tumor protein p63 (p63) is a specific marker for squamous cell carcinomas." (PMID 32485798, 2020). "Collectively, it should be noted that a significant number of SqCCs or adenocarcinomas show a positivity for TTF-1 (clone SPT24) or TP63, respectively." (PMID 29538329, 2018). "Conversely, TP63 is sensitive (positive in 100%) but less specific (positive in 31% of adenocarcinoma)." (PMID 29538329, 2018). "To explore how CCAT1 was regulated by TP63 and SOX2, we analyzed ChIP-seq data of H3K27ac, TP63, and SOX2 generated from SCC cells, and compared them to those from other cells types, including embryonic stem cells and adenocarcinoma cells from various organs." (PMID 30190462, 2018). "Gene amplifications of 3q including SOX2, TP63, PIK3CA, and EPHB3 were observed in as many as 86% of SQC samples but only 21% of adenocarcinoma samples." (PMID 28591695, 2017). "In contrast, the analysis of TP63 transcripts in adenocarcinomas indicated very low abundance or absence of detection in this NSCLC subpopulation." (PMID 35039644, 2022). "In contrast, TP63, a crucial regulatory transcription factor important in development and oncogenesis of epithelial-rich tissues, showed broad and widespread expression across squamous, but not in adenocarcinoma or urothelial tumors." (PMID 35912202, 2022).
genetic disorder (4 papers, 2016 to 2025). "Ankyloblepharon-Ectodermal Defects-Cleft Lip/Palate (AEC) syndrome is a rare genetic disorder caused by mutations in the TP63 gene, which encodes a transcription factor essential for epidermal gene expression." (PMID 39863572, 2025). "Phenotypic descriptions of these VUS are overly general or lacking, such as “TP63‐related spectrum disorders”, “Inborn genetic diseases”, “not provided”." (PMID 40964825, 2025).
infection (4 papers, 2016 to 2025). The state of being infected such as from the introduction of a foreign agent such as serum, vaccine, antigenic substance or organism. "In addition, the infection caused by A. hydrophila resulted in significant changes in the transcription of epithelial proliferation and migration-related genes, including tp63, fat2, and Itgb4, when compared to control fish." (PMID 37908355, 2023). "In contrast, squamous epithelia showed minimal ISG activation and maintained high TP63 activity regardless of infection status." (PMID 41042872, 2025). "TP63, FOXA1, STAT1, ELK1, FOS, and JUN are TFs in various lung injury or infection types." (PMID 36911695, 2023). "By 36 hr post-Lenti-SOX2 infection of plastic basal cell cultures, most cells expressed SOX2 protein, as well as the basal cell marker TP63, but did not yet express markers of overt mucinous or squamous differentiation." (PMID 27880766, 2016).
immune dysfunctions (1 paper, 2024). "Our findings suggest that comprehensive immunological evaluation should be considered for patients with TP63 mutations to better understand and manage potential immune dysfunctions." (PMID 39409174, 2024).
TP63 also shares sentences with these, for which no sentence is quoted: split-hand/foot malformation type 4 (10 papers); orofacial cleft 8 (6); lip (4); Split-Hand/Foot Malformation 4 (4); Hay-Wells syndrome (3); lymph node metastases (3); -hand” (2); adenoid cystic carcinoma (2); DiGeorge syndrome (2); ependymoma (2); hepatocellular carcinoma (2); kidney cancer (2); Li-Fraumeni syndrome (2); Obesity (2); pancreatic ductal adenocarcinoma (2); skin cutaneous melanoma (2); adenoma (1); AEC syndrome (1); amelogenesis imperfecta (1); anodontia (1); athymia (1); autoimmune disease (1); B-cell lymphomas (1); Barrett esophagus (1); breast tumors (1); Char syndrome (1); chordoma (1); Cirrhosis (1); cleft uvula (1); Cognitive impairment (1).
A further 54 diseases each share a sentence with TP63 in 1 paper.